RN7SKP159 (RN7SK pseudogene 159)
Gene: Miscellaneous RNA gene on chromosome 8 (5,910,945 to 5,911,236, reverse strand). Ensembl gene ENSG00000222589.
Homologues: Orthologues: chimpanzee 7SK (90% identical). Paralogues in human: 7SK (78% identical), RN7SKP217 (78% identical), RN7SKP185 (77% identical), RN7SKP133 (77% identical), RN7SKP243 (76% identical), RN7SKP189 (76% identical), RN7SKP211 (76% identical), RN7SKP78 (76% identical), RN7SKP20 (75% identical), RN7SKP203 (75% identical), RN7SKP74 (75% identical), RN7SKP1 (75% identical), and 284 more.